FOXM1 (forkhead box M1)
Diseases named in the same sentence as FOXM1 in open-access papers (continued):
Sharing a sentence is not in itself a finding about the gene and the disease.
cancer (continued). "The result showed that FOXM1 overexpression significantly increased the expression levels of AURKA as well as cancer stem cell markers c-Myc and Nanog, in MCF-7 cells." (PMID 28114286, 2017). "Specificity protein 1 (SP1) and Forkhead Box M1 (FOXM1) also potentiate UHRF1 expression in different cancers." (PMID 28881702, 2017). "FOXM1 Apt is a novel and specific FOXM1 inhibitor, providing a potential reagent for cancer diagnosis and therapy in the future." (PMID 28358012, 2017). "High expression of FOXM1 had already been confirmed to be related to bad prognosis in many other cancer entities." (PMID 28498805, 2017). "Taken together, the expression of FOXM1 is a useful biomarker for the prognosis of human cancers and a potential therapeutic target in RCC cells." (PMID 28902136, 2017). "Consistently, FOXM1 knockdown downregulated the expression levels of cancer stem cell markers SOX2, c-Myc and Nanog, and reduced the mammosphere formation capacity and the CD44hi/CD24lo population in MDA-MB-231 cells." (PMID 28114286, 2017). "These are highly relevant to the fact that FoxM1 is over-expressed in poorly differentiated cancer cells." (PMID 28387346, 2017). "The inactivation of FOXM1 leads to inhibition of progression and/or invasion of these cancers, suggesting FOXM1 as an attractive target for the development of novel anti-cancer therapies." (PMID 28358012, 2017). "In conclusion, high levels of B-MYB, FOXM1, LIN9 and some of their target genes are associated with a poor prognosis in different types of cancer." (PMID 28061449, 2017). "FOXM1 and FOXO3a are known as antagonizing key players in cancer progression, proliferation and drug resistance." (PMID 29228593, 2017). "The aberrant expression of FOXM1 enhanced cancer cell aggressiveness, and high expression of FOXM1 was significantly associated with a poor prognosis of this disease." (PMID 28902136, 2017). "FOXM1 is considered to be an important protein target in cancer diagnosis and therapy, and there are new drugs in the process of being developed that can modulate the function of FOXM1 in the context of carcinogenesis." (PMID 28235006, 2017). "In recent years, the significance of FOXM1 expression has continuously gained growing attention as one of the driving factors in cancer progression." (PMID 29228593, 2017). "The authors proposed the inhibition of FoxM1 as a new therapeutic strategy to kill cancer cells selectively." (PMID 28770020, 2017). "The anti-oxidant function of FoxM1 is particularly important for cancer cells that express reactive oxygen species (ROS) producing oncogenes, such as activated Ras and Akt." (PMID 28387346, 2017). "Consistently, AURKA knockdown downregulated the expression of FOXM1 and that of the cancer stem cell markers c-Myc, SOX2 and Nanog in MDA-MB-231 cells." (PMID 28114286, 2017). "By this way, the transfection of FOXM1 Apt results in the downregulation of the expression of FOXM1 target genes in cells and consequently inhibits cancer cell proliferation." (PMID 28358012, 2017). "FOXM1 is frequently overexpressed in multiple cancers through the activation of specific transcriptional pathways." (PMID 28358012, 2017). "FoxM1 is a member of the Forkhead box (Fox) transcription factor family, which has been shown to be over-expressed in various cancers and studies have shown that alterations in FoxM1 signaling were associated with carcinogenesis." (PMID 28784180, 2017). "As reported, FOXM1 promotes cancer cell survival by activating NF-κB expression under stress conditions." (PMID 28978107, 2017). "Inhibiting FOXM1 transcriptional activities is proposed as a potential therapeutic strategy for cancer treatment." (PMID 28358012, 2017). "NF-kappaB p65 is associated with cell survival and represses essential cell cycle effectors regulated by FOXM1 in other cancers." (PMID 29228593, 2017).
cancer (continued). "To date, several mechanisms have been proposed to explain the activity of FoxM1 in cancer progression, including the activation of FoxM1 by several oncogenic protein and signalling pathways, such as c-Myc, Ras, and PI3K/AKT." (PMID 28770020, 2017). "The expression of FOXM1 was significantly upregulated in cancer tissues compared with normal tissues (p < 0.0001)." (PMID 28902136, 2017). "The oncogene forkhead box M1 was found to interact with Smad3 and sustain the Smad3/Smad4 complex, promoting cancer metastasis induced by TGF-β." (PMID 29183317, 2017). "And FOXM1 overexpression in tumor tissue is also correlated with unfavorable outcome in early stage cancers." (PMID 28427178, 2017). "Previously, the involvement of FOXM1 in resistance to doxorubicin has been reported in various carcinoma cell lines." (PMID 28482906, 2017). "Understanding the regulation of FOXM1 will provide new clues for the identification of reliable and novel therapeutic targets for cancers." (PMID 27542221, 2016). "Since FOXM1 was frequently overexpressed in a broad spectrum of human cancers, we further investigated the effect of FOXM1 acetylation on malignant growth potential." (PMID 27542221, 2016). "Previous studies showed that FOXM1 promotes cancer cell migration and invasion by increasing the activities of MMP2 and MMP9." (PMID 27034162, 2016). "ERK activation has also been shown to be involved in FOXM1 phosphorylation, nuclear translocation, and enhanced FOXM1 transcriptional activity and to promote downstream target gene expression in some cancers." (PMID 26918606, 2016). "It is also notable that TOPK, MELK, and FOXM1 were suggested as cancer stem cell markers and listed in top 30 of the “consensus stemness ranking (CSR) signature” genes." (PMID 26933922, 2016). "We have demonstrated that treatment of cancer cells with either siTOPK or siMELK downregulated FOXM1 both in protein level and in transcriptional level." (PMID 26933922, 2016). "FOXM1 stimulates transcription of pluripotency-related genes in cancer stem cells, which are cells with properties of multi-lineage differentiation and self-renewal capacity." (PMID 27074562, 2016). "To study the physiological role of FOXM1 in this type of cancer, we performed siRNA-mediated knock-down of FOXM1." (PMID 27385468, 2016). "Consistent with its role in cell proliferation, FOXM1 overexpression has been identified in many types of cancers, including liver, prostate, breast, lung, and colon." (PMID 26885609, 2016). "In consistent with our findings, it was also reported that FOXM1 had an important role in the resistance of cancer cells to gefitinib." (PMID 27494877, 2016). "For example, both showed inhibition of FOXM1 and activation of FOXO3—forkhead transcription factors with reciprocally antagonist actions implicated in many cancers and in cardiomyocyte proliferation." (PMID 26138449, 2016). "On the contrary, downregulation of FOXM1 expression leads to cell cycle arrest, chromosome misaggregation and spindle defects in cancer cells." (PMID 27034162, 2016). "It is also reported that FOXM1 can activate the PI3K/Akt/mTOR pathway which is one of dominant oncogenic pathways in human cancer." (PMID 26871945, 2016). "Our results indicate FOXM1 expression as a potential prognostic marker as well as a putative molecular target for cancer therapy." (PMID 27764801, 2016). "FOXM1 is generally high-expressed in human cancers and exerts a critical role in cancer invasion and metastasis." (PMID 27034162, 2016). "Studies have shown that enhanced FOXM1 levels promote cancer cell invasion and metastasis by inducing epithelial-to-mesenchymal transition (EMT)." (PMID 27034162, 2016). "More and more studies found that Foxm1 plays an important role in the occurrence and development of malignant tumors and regulate the tumor progression as a downstream target of Gli1 in cancers like basal cell carcinomas and lung carcinomas." (PMID 27863385, 2016).
cancer (continued). "FOXM1 plays a critical role in carcinogenesis by promoting cancer initiation, progression, and drug response." (PMID 27542221, 2016). "Based on the genomic expression data in the whole cancer population, the top prognostic genes were identified, such as FOXM1, CBX7, CREBL2 and SKP2, which were consistent with previous studies." (PMID 27322207, 2016). "FOXM1 transcription factor has been shown to be amongst the top upregulated oncogenes across 39 cancer types and is a major predictor of poor cancer prognosis." (PMID 27409343, 2016). "The results showed a significant decrease in FOXM1 at both the mRNA and protein levels, indicating that p63 also indirectly controls FOXM1 expression in cancer cells." (PMID 27385468, 2016). "Nevertheless, it has been noted that FOXM1 also plays a role in the development of cancer on a wider scale." (PMID 26922065, 2016). "FOXM1 transcription factor is a crucial regulator of cell proliferation and cell cycle progression that is overexpressed in many types of cancer." (PMID 28040803, 2016). "To date, studies of FOXM1 have been performed only in the context of cancer cell lines and/or immortalized cell lines in which the aberrant genetic background interferes with FOXM1 function." (PMID 27385468, 2016). "This has been further confirmed by independent gene expression profiling studies of cancers, which identified FOXM1 as a commonly up-regulated gene in human solid tumors." (PMID 26885609, 2016). "Both nucleophosmin and FOXM1 tend to co-localize in the nucleolus of cancer cells and RNAi- mediated nucleophosmin knockdown in cancer cells decreases levels of FOXM1." (PMID 27074562, 2016). "Aberrant FOXM1 expression enhances the migration and invasion of cancer cells by upregulating the transcription levels of MMP2 and MMP9." (PMID 27034162, 2016). "Previous studies also have revealed that the AKT signaling pathway upregulates the expression of FOXM1 in cancer cells." (PMID 27494877, 2016). "We predicted that either there should be no change in their expression or there should be concomitant changes with FOXM1 expression ie activating components should go up and/or repressive components should go down in cancer samples." (PMID 25889361, 2015). "We reasoned that as FOXM1 is a transcriptional activator, its target genes should be co-upregulated in cancer cells." (PMID 25889361, 2015). "Accumulating evidence suggests that FOXM1 functions as a proto-oncogene and contributes to the initiation and progression of many types of cancers of the breast, liver, lung, brain and prostate." (PMID 26121260, 2015). "In this study, we clearly demonstrate that miR-34a suppresses the expression of FoxM1 and c-Myc, which activates telomerase activity and extends telomere length, providing a rationale for the accelerated senescence by miR-34a in cancer cells." (PMID 25686834, 2015). "FOXM1 is overexpressed and activated in many human cancers and possesses oncogenic activity in vitro and in vivo." (PMID 26243836, 2015). "The transcription factor FOXM1 was recently shown to induce the expansion of human normal stem cells, as well as of cancer stem-like cells." (PMID 26087310, 2015). "To elucidate this mechanism, we transfected SMMC-7721 and HHCC cancer cells with FoxM1 siRNA and pCDNA3.1-c-Myc." (PMID 25686834, 2015). "FOXM1 inhibitors such as the thiazole antibiotics siomycin A and thiostrepton, induce the apoptosis of many types of cancer cells and have been approved by the Federal Drug Administration for animal use." (PMID 25537512, 2015). "Elevated expression of the transcription factor, Forkhead box M1 (FOXM1), has been reported in various human cancers, and it has been shown to have potential as a target for immunotherapy." (PMID 26640950, 2015). "We found that FOXM1 mRNA expression was elevated in all but one cancer cell line as compared to hOSE cells, and was heterogeneous in the HGSOC cell types." (PMID 26243836, 2015).
cancer (continued). "Based on the oncogenic role of FOXM1 in cancer, there is significant interest in developing drugs that target this protein." (PMID 26243836, 2015). "It has been suggested that the WNT/β-CATENIN and transforming growth factor (TGF-β)/SMAD signaling pathways, acting downstream of FOXM1 targets, drive cancer progression by inducing the EMT." (PMID 25537512, 2015). "Forkhead box M1 (FoxM1) transcription factor is an oncogenic regulator that promotes the proliferation, survival, and treatment resistance of various human cancers." (PMID 26444992, 2015). "In agreement, the effect of FOXM1 overexpression on cell cycle progression in primary hOSE are reminiscent of that reported in cancer cells, although the effects were more robust in the latter." (PMID 26243836, 2015). "How FOXM1 regulates the transport of chemotherapeutic agents into and out of cancer cells via plasma membrane transporters is, however, unclear." (PMID 25537512, 2015). "FOXM1 also triggers cancer progression by promoting a VEGF-dependent angiogenic switch and by facilitating invasion via MMP-2 and MMP-9 secretion." (PMID 25797272, 2015). "As one of the early up-regulated proteins in cancerogenesis, FOXM1 has been demonstrated to contribute to all hallmarks of cancer." (PMID 25797272, 2015). "Abnormal transcription and expression of PTTG1 and FoxM1 are involved in cancer progression and metastasis." (PMID 26264222, 2015). "Despite these caveats, the existence of a small molecule inhibitor of FOXM1 provides a new and exciting opportunity to pursue relevant translational studies in FOXM1-dependent cancers, including HGSOC." (PMID 26243836, 2015). "The Forkhead (FKH) transcription factor FOXM1 is a key regulator of the cell cycle and is overexpressed in most types of cancer." (PMID 26100407, 2015). "This would be of immense interest in the field of oncology as FOXM1 is frequently overexpressed in several cancers." (PMID 26121260, 2015). "An important example of this category is the cancer-related TF FOXM1, which requires a Random Forest model with co-regulatory factor motifs to identify FOXM1 targets in the genome." (PMID 26562774, 2015). "With the transfection of miR-34a duplex (miR-34a) in cancer cell lines, we found that miR-34a reduced the protein levels of c-Myc and FoxM1 significantly." (PMID 25686834, 2015). "Treatment of human cancer cell lines with siomycin A or thiostrepton not only inhibits FOXM1 activity but also its expression." (PMID 25537512, 2015). "Intriguingly, cancer stem cell-like cells are known to express high levels of all the forementioned FoxM1 downstream effectors including WNT, EMT, and Sox2." (PMID 26444992, 2015). "The role of FoxM1 in chemoresistance has been reported in various cancers including GBM, but relatively little is known for radioresistance." (PMID 26444992, 2015). "In many human cancers FOXM1 overexpression promotes aberrant activation of FOXM1 target genes, contributing to oncogenesis and facilitating invasion, metastasis, and therapeutic resistance." (PMID 26100407, 2015). "Dysregulated FOXM1 expression is an early initiating event in cancer and as such it represents a novel therapeutic target." (PMID 26100407, 2015). "In the ongoing search for molecular points of therapeutic intervention for various malignancies, both PTTG1 and FoxM1 have been considered as promising and attractive targets for cancer therapy." (PMID 26264222, 2015). "FOXM1 is another member of the FOX family of transcription factors that contrary to FOXO displays a pro-oncogenic role in cancer." (PMID 26258070, 2015). "A strong association between expression of FoxM1 and Cox-2 with MMP-9 expression has been reported in a number of cancers." (PMID 26159723, 2015).
cancer (continued). "FOXM1 is over-expressed in a variety of human tumors and plays a critical role in cancer development and progression." (PMID 24748173, 2014). "Proteasome inhibitors suppress FOXM1, but paradoxically knockdown of FOXM1 additionally sensitizes human cancer cells to apoptosis induced by proteasome inhibitors." (PMID 25093142, 2014). "Using caspase-3 cleavage as a readout we found that knockdown of FOXM1 increased cell death in human cancer cells induced by proteasome inhibitors about 2-fold." (PMID 25093142, 2014). "We found that the combinations of ROS inducers with FOXM1/proteasome inhibitors stimulated robust apoptosis in human cancer cell lines." (PMID 25093142, 2014). "Forkhead Box M1 (FoxM1), a member of the Forkhead family of transcription factors, is overexpressed in the majority of human cancers." (PMID 25426548, 2014). "Using RNA-interference or proteasome inhibitors to inhibit FOXM1 we found that suppression of FOXM1 sensitized human cancer cells to apoptosis induced by DNA-damaging agents or oxidative stress." (PMID 25093142, 2014). "Thiostrepton downregulates FoxM1 expression in several cancer cell lines and enhances sensitivity to carboplatin in vivo." (PMID 25426548, 2014). "The principal roles played by FoxM1 in different aspects of cancer initiation and progression render it a prime target for pharmaceutical intervention." (PMID 25401090, 2014). "FOXM1 is involved in hallmarks of cancer by regulating numerous target genes, including JNK1, which is involved in invasion and metastasis, and p21, which is involved in cell proliferation." (PMID 24918286, 2014). "Collectively, our results not only extend the conclusion that FOXM1 is involved in the hallmarks of cancer processes but also provide the novel mechanism of how SUMOylatgion regulates FOXM1B activity." (PMID 24918286, 2014). "It has been shown that FOXM1, which is overexpressed in a majority of human tumors, protects cancer cells from oxidative stress." (PMID 25093142, 2014). "Recent evidence also implicates FOXM1 deregulation in the development of cancer genotoxic therapeutic agent resistance." (PMID 25287128, 2014). "Since FOXM1 is suppressed by proteasome inhibitors, we decided to test combination treatment of human cancer cells with proteasome inhibitors together with DNA-damaging agents." (PMID 25093142, 2014). "Accordingly, genome-wide profiling studies of gene expression in cancers have independently confirmed that FOXM1 is one of the most frequently upregulated genes in human malignancies." (PMID 25287128, 2014). "We decided to examine functions of FOXM1 in apoptosis by developing human cancer cell lines with stable FOXM1 knockdown and analyzing their responses to different anticancer agents." (PMID 25093142, 2014). "FOXM1 is the relay center in multiple hallmarks of cancer by targeting downstream genes for cancer development, such as proliferation, epithelial-mesenchymal transition (EMT), invasion, and metastasis." (PMID 24918286, 2014). "Collectively, our findings uncover novel roles for FOXM1 and FOXM1-regulated genes in promoting cancer stem-like cell properties and therapy resistance." (PMID 25213081, 2014). "Conversely, FOXM1 is also a potent oncogenic factor that is essential for cancer initiation, progression and drug resistance." (PMID 25287128, 2014). "Apart from cancer initiation, there is convincing evidence that FoxM1 also has a vital role in angiogenesis, invasion, metastasis, DNA damage repair, and the development of chemotherapeutic drug resistance." (PMID 25401090, 2014). "There is compelling evidence that FoxO3a and FoxM1 have opposite roles in cancer: while FoxO3a behaves like a typical tumor suppressor, FoxM1 functions as a potent oncogene." (PMID 25401090, 2014). "In contrast to FOXO1, FOXM1 shows oncogenic activities and targeting FOXM1 induces apoptosis in cancer cells." (PMID 25010679, 2014).